VWA3B (von Willebrand factor A domain containing 3B)
Synonyms: DKFZp686F2227; MGC26733; SCAR22
Tractability: PROTAC: ubiquitination databases record sites on it.
Gene: Protein-coding gene on chromosome 2 (98,087,116 to 98,313,299, forward strand). Ensembl gene ENSG00000168658.
Subcellular location: Cytoplasm
Subcellular location (Human Protein Atlas): Cytosol; Nucleoplasm
Gene Ontology:
Cellular component: cytoplasm; cytosol
Genetic constraint (gnomAD): Loss-of-function variants: 134 observed, 155.92 expected, observed/expected ratio (o/e) 0.86, 90% interval 0.75 to 0.99. The upper end of that interval is the gene's LOEUF score, 0.99, which puts it in group 4 of 6, group 1 being the genes least tolerant of losing a copy. Missense variants: 1,551 observed, 1,608 expected, observed/expected ratio (o/e) 0.96, 90% interval 0.92 to 1.01. Synonymous variants: 595 observed, 605.23 expected, observed/expected ratio (o/e) 0.98, 90% interval 0.92 to 1.05.
Homologues: Orthologues: chimpanzee VWA3B (99% identical), macaque VWA3B (93% identical), dog VWA3B (79% identical), pig VWA3B (76% identical), mouse Vwa3b (68% identical), rat Vwa3b (68% identical), tropical clawed frog vwa3b (39% identical). Paralogues in human: ITIH3 (13% identical), ITIH4 (11% identical), ITIH1 (11% identical), ITIH2 (11% identical), ITIH6 (10% identical), VWA5B1 (10% identical), VWA3A (10% identical), ITIH5 (10% identical), PARP4 (9% identical), VWA5B2 (9% identical), VWA5A (9% identical).
Diseases named in the same sentence as VWA3B in open-access papers:
VWA3B is named in the same sentence as 9 diseases in open-access papers, as found by Europe PMC text mining. Sharing a sentence is not in itself a finding about the gene and the disease. The quoted sentences say what the papers report.
Ataxia (2 papers, 2020 to 2023). Ataxia refers to impaired coordination of voluntary muscle movement. "Previously, four variants including three nonsense and one missense have been reported in VWA3B underlying neurological phenotypes including intellectual disability, cerebellar ataxia and autism spectrum disorder as per HGMD (Accessed on 20-May-2022)." (PMID 37772257, 2023). "We, therefore, supplemented the EOAD- control group with ataxia genotypes that were not reported with comorbid dystonia in literature (including ABHD12; IFRD1; KIAA0226; PHYH; TDP1; VWA3B; GTF2H5; FLVCR1; ACO2; HSD17B4; DNAJC3 gene mutations; PubMed and OMIM)." (PMID 33255407, 2020).
tongue squamous cell carcinoma (1 paper, 2019). A squamous cell carcinoma that arises from the tongue. "In addition, VWA3B is significantly differentially expressed in tongue squamous cell carcinoma samples at the transcriptome level." (PMID 31921812, 2019).
VWA3B also shares sentences with these, for which no sentence is quoted: autism spectrum disorder (1 paper); bladder (1); bladder urothelial carcinoma (1); cancer (1); cerebellar ataxia (1); Dystonia (1); Intellectual disability (1).